CCNF (cyclin F)
Description:
Substrate recognition component of a SCF (SKP1-CUL1-F-box protein) E3 ubiquitin-protein ligase complex which mediates the ubiquitination and subsequent proteasomal degradation of target proteins. The SCF(CCNF) E3 ubiquitin-protein ligase complex is an integral component of the ubiquitin proteasome system (UPS) and links proteasome degradation to the cell cycle. Mediates the substrate recognition and the proteasomal degradation of various target proteins involved in the regulation of cell cycle progression and in the maintenance of genome stability. Mediates the ubiquitination and proteasomal degradation of CP110 during G2 phase, thereby acting as an inhibitor of centrosome reduplication. In G2, mediates the ubiquitination and subsequent degradation of ribonucleotide reductase RRM2, thereby maintaining a balanced pool of dNTPs and genome integrity. In G2, mediates the ubiquitination and proteasomal degradation of CDC6, thereby suppressing DNA re-replication and preventing genome instability. Involved in the ubiquitination and degradation of the substrate adapter CDH1 of the anaphase-promoting complex (APC/C), thereby acting as an antagonist of APC/C in regulating G1 progression and S phase entry. May play a role in the G2 cell cycle checkpoint control after DNA damage, possibly by promoting the ubiquitination of MYBL2/BMYB.
Synonyms: FBX1; FBXO1; FTDALS5
Tractability: PROTAC: UniProt records ubiquitination sites on it; ubiquitination databases record sites on it.
Gene: Protein-coding gene on chromosome 16 (2,429,394 to 2,458,854, forward strand). Ensembl gene ENSG00000162063.
Subcellular location: Nucleus; Cytoplasm, perinuclear region; Cytoplasm, cytoskeleton, microtubule organizing center, centrosome, centriole
Subcellular location (Human Protein Atlas): Nucleoplasm; Centrosome; Cytosol
Pathways (Reactome):
Immune System: Antigen processing: Ubiquitination & Proteasome degradation
Metabolism of proteins: Neddylation
Gene Ontology:
Molecular function: anaphase-promoting complex binding; protein binding; ubiquitin-like ligase-substrate adaptor activity; cyclin-dependent protein serine/threonine kinase regulator activity
Biological process: negative regulation of centrosome duplication; protein ubiquitination; regulation of cell cycle; SCF-dependent proteasomal ubiquitin-dependent protein catabolic process; regulation of cell cycle process
Cellular component: centriole; centrosome; cytosol; nucleoplasm; nucleus; SCF ubiquitin ligase complex; cyclin-dependent protein kinase holoenzyme complex; microtubule organizing center; perinuclear region of cytoplasm
Genetic constraint (gnomAD): Loss-of-function variants: 29 observed, 74.42 expected, observed/expected ratio (o/e) 0.39, 90% interval 0.29 to 0.53. The upper end of that interval is the gene's LOEUF score, 0.53, which puts it in group 2 of 6, group 1 being the genes least tolerant of losing a copy. Missense variants: 869 observed, 980.78 expected, observed/expected ratio (o/e) 0.89, 90% interval 0.84 to 0.94. Synonymous variants: 423 observed, 419.85 expected, observed/expected ratio (o/e) 1.01, 90% interval 0.93 to 1.09.
Gene-disease validity (ClinGen):
ClinGen rates the evidence that CCNF causes each of these diseases.
frontotemporal dementia and/or amyotrophic lateral sclerosis 5 (autosomal dominant): Limited.
Homologues: Orthologues: chimpanzee CCNF (99% identical), macaque CCNF (97% identical), pig CCNF (87% identical), guinea pig CCNF (86% identical), rabbit CCNF (86% identical), dog CCNF (86% identical), rat Ccnf (85% identical), mouse Ccnf (83% identical), tropical clawed frog ccnf (61% identical), zebrafish ccnf (51% identical), Caenorhabditis elegans cye-1 (11% identical), Drosophila melanogaster CycB (11% identical), and 6 more. Paralogues in human: CCNA2 (13% identical), CCNB1 (12% identical), CCNB2 (12% identical), CCNB3 (12% identical), CCNA1 (11% identical), CCNE2 (9% identical), CCNE1 (9% identical), CCNP (9% identical), CCNO (8% identical), CCND2 (8% identical), CCND3 (8% identical), CCND1 (8% identical), and 6 more.
Diseases named in the same sentence as CCNF in open-access papers:
CCNF is named in the same sentence as 81 diseases in open-access papers, as found by Europe PMC text mining. Sharing a sentence is not in itself a finding about the gene and the disease. The quoted sentences say what the papers report.
frontotemporal dementia (14 papers, 2016 to 2025). Frontotemporal dementia (FTD) comprises a group of neurodegenerative disorders, characterized by progressive changes in behavior, executive dysfunction and language impairment, as a result of degeneration of the medial prefrontal and frontoinsular cortices. "Cyclin F (CCNF) variants have been found to be associated with amyotrophic lateral sclerosis (ALS)/frontotemporal dementia (FTD)." (PMID 37171577, 2023). "Ian Blair and colleagues use genome-wide linkage analysis and whole exome sequencing to identify mutations in the CCNF gene in large cohorts of amyotrophic lateral sclerosis and frontotemporal dementia patients." (PMID 27080313, 2016). "Amyotrophic lateral sclerosis (ALS)- and frontotemporal dementia (FTD)-linked mutations in CCNF have been shown to cause dysregulation to protein homeostasis." (PMID 37243816, 2023). "These variants map to the CCNF, DCTN1, and NOTCH3 genes, which are involved in the ALS/frontotemporal dementia (FTD) spectrum." (PMID 36133075, 2022). "Previous research has identified CCNF mutations in familial (FALS) and sporadic amyotrophic lateral sclerosis (SALS), as well as in frontotemporal dementia (FTD)." (PMID 30008669, 2018). "E3 ligase complex SCFcyclinF ubiquitylates p62 at K281, promoting the aggregation of p62 into the insoluble, whereas mutant cyclin F promotes aberrant p62 ubiquitination and insolubility in ALS and frontotemporal dementia (FTD) Pathogenesis." (PMID 40643536, 2025). "Although not examined in a cancer context, an interaction between cyclin F and SFPQ is of clinical relevance to familial and sporadic amyotrophic lateral sclerosis (ALS) and frontotemporal dementia (FTD)." (PMID 40276932, 2025).
amyotrophic lateral sclerosis (13 papers, 2016 to 2025). Amyotrophic lateral sclerosis (ALS) is a neurodegenerative disease characterized by progressive muscular paralysis reflecting degeneration of motor neurons in the primary motor cortex, corticospinal tracts, brainstem and spinal cord. "Missense mutations in CCNF encoding for Cyclin-F are associated with amyotrophic lateral sclerosis (ALS)." (PMID 36114006, 2022). "Furthermore, mutations in CCNF, the Cyclin-F gene, are associated with amyotrophic lateral sclerosis (ALS)." (PMID 36114006, 2022). "Differential methylation was reported in RAD9B and C8orf46, CCNF, DPP6, RAMP3, and CCS genes in monozygotic twins and triplets discordant for amyotrophic lateral sclerosis." (PMID 34200232, 2021).
breast carcinoma (12 papers, 2019 to 2025). "The observed phenotype of increased DNA replication stress and accumulation of DNA damage upon Chk1 inhibition in Rb‐deficient breast cancer cell lines closely resembles the DNA replication catastrophe mediated by cyclin F loss and E2F1 deregulation." (PMID 31424118, 2019). "Similarly, in breast cancer, CCNF overexpression has been associated with increased malignancy and a higher risk of metastatic recurrence, indicative of an adverse prognosis." (PMID 37670965, 2023). "To date, no other diseases associated with CCNF mutations have been identified, although elevated cyclin F expression levels have been correlated with poorer prognosis in patients with hepatocellular carcinoma, clear cell renal cell carcinoma, ovarian cancer, and breast cancer." (PMID 40282367, 2025). "However, the underlying mechanisms of action of CCNF in breast carcinoma remain unclear and under-explored." (PMID 34201347, 2021). "To investigate the elevated expression of CCNF in tumors, we focused on breast cancer, which serves as a representative human cancer type, for further investigation." (PMID 37670965, 2023). "Previous studies have demonstrated elevated CCNF expression in breast cancer 16, melanoma 24, colorectal cancer 25, gastric cancer 26, ovarian cancer 15, liver cancer 27, and pancreatic cancer 28, and g which were associated with unfavorable patient outcomes." (PMID 37670965, 2023). "Through qRT-PCR and WB analyses, it was observed that CCNF exhibited significant upregulation in breast cancer cells, namely MCF-7, MDA-MB-453, ZR-75-30, and SK-BR-3, when compared to the normal breast cancer cell line MCF10A." (PMID 37670965, 2023). "At the same time, our study also found that the expression level of CCNF protein was high in many cancer tissues, especially in breast cancer, colorectal cancer, and stomach cancer tissues." (PMID 37168372, 2023). "To better understand the pathophysiological functions of the identified F-boxes (FBXO43, FBXO15, and CCNF) in BRCA, we performed specific-RNAi knockdown in breast carcinoma cells to assess the potential loss/gain-of-functions." (PMID 34201347, 2021). "Additionally, the in vitro experiments showed that silencing cyclin F reduces proliferation rate and migration of breast cancer cells." (PMID 38654021, 2024). "Similarly, the study presented by Liu and colleagues demonstrated a strong relationship between high CCNF mRNA levels and worse prognosis in breast cancer (BC) patients." (PMID 38654021, 2024). "Furthermore, we validated the differential expression of CCNF in normal human breast cancer and breast cancer cell lines using experimental verification." (PMID 37670965, 2023). "In addition, CCNF was an adverse prognostic factor in terms of distant metastasis-free survival (DMFS) in patients with breast cancer and for distant relapse-free survival (DRFS) in patients with soft tissue liposarcoma (P<0.01)." (PMID 37168372, 2023). "CCNF protein staining intensity was moderate in cervical cancer, endometrial cancer, liver cancer, ovarian cancer, pancreatic cancer, and urothelial cancer and high in breast cancer, colorectal cancer and stomach cancer." (PMID 37168372, 2023). "Furthermore, we experimentally verified the high expression of CCNF in breast cancer cells, establishing its correlation with clinical diagnosis, prognosis, and DNA methylation." (PMID 37670965, 2023). "Interestingly, among all 71 F-box family members, there are four F-boxes (FBXO43, FBXO15, FBXL8, and CCNF) with significantly upregulated mRNA levels in breast carcinoma tissues." (PMID 34201347, 2021). "Furthermore, we verified the high expression of CCNF in breast cancer by RT-qPCR and WB analysis." (PMID 37670965, 2023). "We examined endogenous proteins corresponding to CDK-RB network genes that correlate most strongly with CCNF using two breast cancer cell lines, MCF-7 and T47D, engineered for doxycycline-inducible expression of cyclin F." (PMID 34851822, 2021).
breast carcinoma (continued). "We found that eight cyclins (CCNA2, CCNB1, CCNB2, CCND2, CCNE1, CCNE2, CCNF, CCNO) were differentially expressed between breast cancer and normal tissue samples, with the cut-off criterion of log2(fold change) >1, p < 0.05." (PMID 33791304, 2021). "Importantly, these observations have been confirmed on the protein level where high expression of cyclin F was observed in Luminal A, Luminal B, HER2, and TNBC breast cancer." (PMID 38654021, 2024). "CCNF was an adverse prognostic factor in terms of OS for patients with brain astrocytoma, brain glioma and breast cancer and in terms of RFS for patients with breast cancer and lung adenocarcinoma." (PMID 37168372, 2023).
hepatocellular carcinoma (11 papers, 2019 to 2025). A malignant tumor that arises from hepatocytes. "Cyclin F (CCNF) dysfunction has been implicated in various forms of cancer, offering a new avenue for understanding the pathogenic mechanisms underlying hepatocellular carcinoma (HCC)." (PMID 34397798, 2021). "FBXO1 (CCNF) had been reported to be downregulated in hepatocellular carcinoma and was related to poor differentiation and adverse clinical outcome." (PMID 35046938, 2021). "Cyclin F (FBXO1) is yet another F-box protein suspected to be a tumor suppressor as it is under-expressed in ~60% of hepatocellular carcinomas and reduced expression correlates with increased tumor sizes and numbers, advanced grade, stage and poor patient outcomes." (PMID 34445249, 2021). "CCNF was proposed to play a cancer-suppressive role in hepatocellular carcinoma." (PMID 34201347, 2021). "Interestingly, the F-box CCNF (known as a cancer suppressor in hepatocellular carcinoma) followed an opposite trend; although its mRNA level was upregulated, its protein level was downregulated." (PMID 34201347, 2021). "CCNF was reported to be significantly repressed in hepatocellular carcinoma tissues." (PMID 34201347, 2021). "Low CCNF expression has been found in hepatocellular carcinoma (HCC) and is connected with a poor prognosis." (PMID 31739630, 2019).
ovarian carcinoma (10 papers, 2021 to 2025). A malignant neoplasm originating from the surface ovarian epithelium. "In that study, the authors demonstrated that CCNF is transcriptionally activated by FOXM1 in an ovarian cancer cell line." (PMID 38916959, 2024). "Dual roles have been described for cyclin F67,68, and our results follow the example of the ovarian cancer where cyclin F enhanced proliferation and invasion of cancer cells and was linked with a poor prognosis in patients." (PMID 38740853, 2024). "However, studies have also shown that the overexpression of CCNF predicts a poor prognosis in ovarian cancer, liver cancer and skin melanoma, suggesting that CCNF is an oncogene." (PMID 37168372, 2023). "Notably, recent studies have highlighted the upregulation of CCNF in ovarian cancer, with high CCNF expression correlating with unfavorable prognostic outcomes in ovarian cancer patients." (PMID 37670965, 2023). "Moreover, our data support that Cyclin F and KIF20A are involved in FOXM1-mediated ovarian cancer formation and development, and high Cyclin F and KIF20A expression was associated with poor prognosis in patients with ovarian cancer." (PMID 36359787, 2022). "Our laboratory also demonstrated that Cyclin F and KIF20A are involved in FOXM1-mediated ovarian cancer cell proliferation and metastasis, and high expression of Cyclin Fand KIF20A was associated with poor prognosis in patients with ovarian cancer." (PMID 36359787, 2022). "Then, we demonstrated that exosomes secreted by HO-ADSCs (HO-ADSC exosomes) enhanced ovarian cancer cell function, and further mechanistic studies showed that the FOXM1, Cyclin F, KIF20A, and MAPK signaling pathways were involved in this process." (PMID 36359787, 2022). "Moreover, OCT4 induces the expression of protein phosphatase 1 (PP1) inhibitors: the nuclear inhibitor of PP1 (NIPP1) and cyclin F (CCNF), which prevents the PP1-dependent de-phosphorylation of Rb, and accelerates cell proliferation in ovarian cancer." (PMID 37760529, 2023). "In addition, we demonstrated that HO-ADSC exosomes promote the growth and metastasis of ovarian cancer cells via a mechanism dependent on the FOXM1, Cyclin F KIF20A, and MAPK signaling pathways." (PMID 36359787, 2022).
melanoma (7 papers, 2013 to 2024). A malignant, usually aggressive tumor composed of atypical, neoplastic melanocytes. "Our former analysis on melanoma and pancreatic adenocarcinoma also revealed that high CCNF mRNA level was associated with a worse prognosis for the patients." (PMID 38654021, 2024). "In terms of clinical significance, the results obtained here are in line with our recent non-pancreas cancer in silico study, in which overexpression of CCNF mRNA was associated with a worse survival of melanoma patients." (PMID 33670609, 2021). "Gagat, Krajewski, Grzanka, and Grzanka (2018) revealed that high expression of CCNF in melanoma patients was associated with worse overall survival." (PMID 31087508, 2019). "High CCNF expression was associated with a poor outcome in melanoma patients." (PMID 31739630, 2019). "The bioinformatics analysis of melanoma patients pointed to CCNF as a negative prognostic marker, and it was reasonable to consider CCNF as an oncogene." (PMID 38654021, 2024). "Another gene down-modulated by D6 in melanoma cells (and not in fibroblasts) is the CCNF gene (FC = 0.24), codifying for cyclin F, the founding member of the F-box protein family." (PMID 23642048, 2013).
gastric cancer (6 papers, 2019 to 2023). A primary or metastatic malignant neoplasm involving the stomach. "Additionally, with gene network reconstruction, CCNF was regarded as one of the main drivers in cell cycle network in gastric cancer." (PMID 31087508, 2019). "To understand the mechanism underlying the cell cycle arrest of gastric cancer cells induced by knocking down AURKB, we next examined the effect of AURKB on various key cell cycle regulatory molecules, including CCND1, CDC16, CDC6, CDC26, CCNB2, CCNF, p27 and E2F1, in gastric cancer cells." (PMID 31982864, 2020). "Similarly, using bioinformatics analysis, another concurrent study has shown that a G2/M checkpoint-related signature composed of five genes (MARCKS, CCNF, MAPK14, INCENP, and CHAF1A) was connected with the prognosis of gastric cancer (GC) patients." (PMID 35419294, 2022).
colorectal cancer (5 papers, 2004 to 2023). A primary or metastatic malignant neoplasm that affects the colon or rectum. "A previous study also showed that high expression of CCNB1 and CCNF was significantly correlated with favorable prognosis in colorectal cancer, which is in agreement with our findings." (PMID 33996604, 2021). "Consistently, CCNA2, CCNB1, CCND1, and CCNF have been observed to be upregulated in colorectal cancer, but there is no clear evidence that CCNE1 and CCNJL are also differentially expressed between colon tumor and normal tissues." (PMID 33996604, 2021).
glioma (5 papers, 2021 to 2024). A benign or malignant brain and spinal cord tumor that arises from glial cells (astrocytes, oligodendrocytes, ependymal cells). "In this report it was shown that metabolic stress resulted in a cyclin F-dependent polyubiquitylation of RBPJ in glioma cells, followed by proteasomal degradation." (PMID 36293193, 2022). "For example, metabolic stress in glioma cells resulted in the induction of cyclin F in a FOXO1-dependent manner that leads to RBPJ proteolysis." (PMID 36293193, 2022). "Moreover, cyclin F levels correlated with glioma formation in a mouse tumour model." (PMID 36293193, 2022). "Therefore, abrogation of CCNF expression facilitates IDH1-R132H-mediated tumorigenesis and metastasis in glioma; that is, CCNF may serve as a tumor suppressor in glioma." (PMID 34397798, 2021). "Under metabolic stress conditions, cyclin F but not cyclin A, cyclin B, cyclin D, or cyclin E is expressed frequently in glioma cell lines." (PMID 37821870, 2023). "Under metabolic stress, FOXO1 increases Cyclin F but not other Cyclins in gliomas, suppressing IDH1 expression, an essential tumor marker which its overexpression is implicated in glioma progression." (PMID 37821870, 2023). "In more detail, the binding of FOXO1 but not FOXO3a, FOXO4, or FOXO6 to cyclin F promoter subsequently represses the expression of IDH1 as a crucial proto-oncogene in glioma." (PMID 37821870, 2023).